CIB3 (calcium and integrin binding family member 3)
Description:
Acts a an auxiliary subunit of the sensory mechanoelectrical transduction (MET) channel in hair cells (By similarity). Plays a role in regulating hair cell MET channel localization and function (By similarity).
Synonyms: KIP3
Tractability: Antibody: the Human Protein Atlas places it where antibodies can reach.
Gene: Protein-coding gene on chromosome 19 (16,161,368 to 16,173,525, reverse strand). Ensembl gene ENSG00000141977.
Subcellular location (Human Protein Atlas): Cytosol; Plasma membrane
Gene Ontology:
Molecular function: calcium ion binding; magnesium ion binding; protein binding
Biological process: calcium ion homeostasis
Genetic constraint (gnomAD): Loss-of-function variants: 22 observed, 24.59 expected, observed/expected ratio (o/e) 0.89, 90% interval 0.64 to 1.28. The upper end of that interval is the gene's LOEUF score, 1.28, which puts it in group 5 of 6, group 1 being the genes least tolerant of losing a copy. Missense variants: 258 observed, 258.35 expected, observed/expected ratio (o/e) 1, 90% interval 0.9 to 1.11. Synonymous variants: 93 observed, 101.35 expected, observed/expected ratio (o/e) 0.92, 90% interval 0.77 to 1.09.
Homologues: Orthologues: chimpanzee CIB3 (99% identical), macaque CIB3 (98% identical), dog CIB3 (98% identical), pig CIB3 (95% identical), mouse Cib3 (94% identical), rat Cib3 (93% identical), rabbit CIB3 (92% identical), tropical clawed frog cib3 (80% identical), guinea pig CIB3 (79% identical), zebrafish cib3 (73% identical), Drosophila melanogaster Cib2 (55% identical), Caenorhabditis elegans calm-1 (49% identical), and 5 more. Paralogues in human: CIB2 (61% identical), CIB1 (40% identical), CIB4 (34% identical), PPP3R1 (27% identical), PPP3R2 (25% identical), CHP1 (24% identical), TESC (23% identical), CHP2 (21% identical).
Diseases named in the same sentence as CIB3 in open-access papers:
CIB3 is named in the same sentence as 4 diseases in open-access papers, as found by Europe PMC text mining. Sharing a sentence is not in itself a finding about the gene and the disease. The quoted sentences say what the papers report.
asthma (1 paper, 2025). "We observed that extreme low temperature decreased Wfdc21, Cttnbp2, Cib3, and Cma1 expression in mild and moderate asthma, while increased expression in severe asthma." (PMID 40313552, 2025). "We observed that the pediatric asthma subjects in the extreme high temperature group exhibited higher expression of Tiam2 and Cma1, whereas Wfdc21, Cib3, and Sftpc expression were decreased." (PMID 40313552, 2025). "Pediatric asthma subjects in the extreme low temperature group showed decreased expression of Wfdc21, Cib3, Cma1, and Dld, while Sftpc and Nxnl expression increased." (PMID 40313552, 2025). "Adult asthma subjects in the extreme temperature fluctuation group showed consistently decreased Wfdc21, Cib3, Gpr171, and Cttnbp2 expression, while increased Tiam2 and Cma1 expression." (PMID 40313552, 2025). "Extreme low temperature decreased Wfdc21, Cttnbp2, Cib3, and Cma1 expression in mild and moderate asthma, while increased expression in severe asthma." (PMID 40313552, 2025). "Further, extreme temperature fluctuations consistently led to decreased expression of Wfdc21, Cib3, Gpr171, and Cttnbp2 in mice and asthma patients." (PMID 40313552, 2025). "Extreme temperature decreased Wfdc21, Cttnbp2, Cib3, and Cma1 expression in mild and moderate asthma, while increased expression in severe asthma patients." (PMID 40313552, 2025). "In addition, asthma subjects in the extreme temperature fluctuation group showed decreased expression of Wfdc21, Cib3, Gpr171, and Cttnbp2, while Tiam2 and Cma1 expression increased." (PMID 40313552, 2025). "Cib3, and Cma1 were significantly upregulated in severe asthma patients." (PMID 40313552, 2025).
deafness (1 paper, 2024). An inherited or acquired condition characterized by the complete loss of the ability to hear from one or both ears. "Mechanotransduction currents are abolished in mice with null mutations in CIB2 and CIB3, resulting in deafness." (PMID 38354260, 2024).
Hearing impairment (1 paper, 2025). A decreased magnitude of the sensory perception of sound. "Notably, CIB2 mutations have been genetically linked to human hereditary hearing impairment, yet the AAV-based restoration of Cib2 or its paralog Cib3 in Cib2-mutant mice remains unexplored." (PMID 40076845, 2025).
cancer (1 paper, 2025). A tumor composed of atypical neoplastic, often pleomorphic cells that invade other tissues. "In addition, previous study highlighted that Cib3 high-expression group was mainly enriched in glycerolipid metabolism, folate biosynthesis, cancer-related pathways, and immune response." (PMID 40313552, 2025).